ENSG00000307861 (novel transcript, antisense to PLEKHG2)
Gene: Long non-coding RNA gene on chromosome 19 (39,412,099 to 39,413,407, reverse strand). Ensembl gene ENSG00000307861.
Gene Ontology:
Molecular function: triplet codon-amino acid adaptor activity
Biological process: translation